S100A9 (S100 calcium binding protein A9)
Diseases named in the same sentence as S100A9 in open-access papers (continued):
Sharing a sentence is not in itself a finding about the gene and the disease.
tumor (continued). "On the other hand, Ep-CAM, 14-3-3 protein theta, S100A9, and OTase categorized both healthy non-tumor and superficial tumor tissues." (PMID 39195201, 2024). "More importantly, S100A9 may promote the malignant progress of GBM by involving in some carcinogenic pathways and remodeling the tumor microenvironment (TME)." (PMID 39137310, 2024). "EC-SOD was found to be a less-abundant protein in superficial tumor samples, in contrast to S100A9, leading to a lack of defense against ROS in the extracellular environment." (PMID 39195201, 2024). "utilized knockout mouse models to show that S100A9 gene expression was required for development of suppressive MDSCs, and that the lack of S100A9 had a beneficial effect during tumor challenge." (PMID 39497822, 2024). "We used recombinant S100A9 protein and CT26 tumor cell supernatant (CT26 sup) as migratory stimuli." (PMID 39497822, 2024). "Further validation of S100A9 Ma’ pro-tumor traits in bulk data, using single-sample gene set enrichment analysis (ssGSEA) in TCGA-GBM to calculate S100A9 Ma scores, showed that patients with high infiltration scores had significantly poorer prognoses than those with low scores." (PMID 39136841, 2024). "We also examined the 825 significantly changed genes differentially expressed in ALDH+ CSCs, which identified S100P and S100A9 as the top two genes most significantly inhibited in ALDH+ CSCs but not ALDH- bulk tumor cells upon XIST KD." (PMID 36922677, 2023). "In those patients, the correlation between the serum and tumor tissue levels was marginal for S100A8 (r = 0.38, P = 0.060), while a significant positive correlation was noted between the serum and tumor tissue levels of S100A9 (r = 0.41, P = 0.042)." (PMID 37280516, 2023). "Altogether, these data illustrate the pro-tumoral effect of intracellular S100A9 in AML, regulating mTOR-ER stress signaling pathways which may contribute to tumor progression and drug resistance." (PMID 38110349, 2023). "Indicating their origin from S100A9 MDSCs, it was also found that the percentage of blood S100A9 MDSCs was closely correlated with the counts of S100A9 cells and CD68 TAM in tumor tissue, and patients with higher S100A9 and CD68 cell numbers also showed worse PFS." (PMID 36817434, 2023). "Indeed, the modifications induced by the doxorubicin/GTN combination on the tumor microenvironment and on the PMN-MDSCs (FATP2, CXCR2, NOS2, S100A9) are in favor of reprogramming these cells towards a less immunosuppressive PMN type phenotype." (PMID 37370739, 2023). "As expected, little-to-no neutrophil infiltration was observed in the sham non-tumor bearing mice, as indicated by the lack of S100A9 staining." (PMID 36614196, 2023). "Following their transcription, translation, and secretion, S100A8 and S100A9 might interact with RAGE, resulting in amplified RAGE signaling and increased tumor growth." (PMID 37627239, 2023). "In animal models, compared to controls, anaplastic thyroid carcinoma cells with S100A8 knockdown showed less lung metastasis and tumor load by tail vein injection, whereas S100A9 knockdown did not affect tumorigenesis and metastasis." (PMID 37701037, 2023). "•Blockade of RAGE prevents S100A9 induction of radioresistance in multiple experimental models of BMs sensitizing the tumor but without detectable toxicity." (PMID 36652782, 2023). "We previously reported that S100A9 could enhance HCC stemness through activating nuclear factor-kappa B (NF-κB) pathway, which may promote tumor progression." (PMID 37133437, 2023). "S100A9 is a calcium-binding protein, mainly secreted by granulocytes and monocytes, and has been reported to be essential for MDSC survival and accumulation in tumor-bearing mice including MM and lymphoma models." (PMID 36304465, 2022). "In addition, S100A9 is known to be secreted from myeloid-derived suppressor cells (MDSC) and serves as a chemoattractant that promotes MDSC recruitment and tumor signaling pathways." (PMID 35454108, 2022).
tumor (continued). "Macrophage in this cluster had high expression of type I interferon signaling related genes (IFITM3, IFI27, MX1, IFI6, and ISG15) as well as gene features related to immunosuppressive phenotype (APOE, APOC1, S100A9, and GPNMB), whereby participating in tumor immune regulation." (PMID 35265520, 2022). "Mechanistically, we showed that MDSC-derived exosomal S100A9 increased circMID1 expression to sponge miR-506-3p, which might then lead to increased MID1 expression and accelerate tumor progression." (PMID 35918733, 2022). "Activated S100A9 binds to PRR receptor RAGE in the tumour microenvironment and blocks host-mediated antitumor immune response targeting tumour cells, in doing so enabling tumour progression." (PMID 35203390, 2022). "We found that the mRNA levels of S100a8/S100a9 were increased in MTMG tissues at multiple developmental stages and tumor tissues, S100a9 expression was increased dramatically in luminal and stromal subpopulations, and Brca1-MT mammary epithelial cell line (G600)." (PMID 35304461, 2022). "In addition to the expression of S100A8 and S100A9 by the tumor cells themselves, a remarkable influx of S100A8+S100A9+ immune cells was detected." (PMID 36303837, 2022). "Tumor cell migration and invasion are facilitated by the upregulation of matrix metalloproteinase expression and inhibited by the downregulation of S100A8 or S100A9, which correlates with their abnormal expression in many cancer types." (PMID 35783639, 2022). "The performance of the models for lower grade cancer is not surprising given the roles of S100A8 and S100A9 in recruitment of immune cells essentially prepping the tissue for tumor formation." (PMID 36284356, 2022). "We detected a high number of CD15+ infiltrating and tumor-intersecting cells in PeCa specimens but not in adjacent normal foreskin with an overlap of S100A8+S100A9+ and CD15+ immune cells." (PMID 36303837, 2022). "However, some members of the S100 family have been reported to be tumor suppressors, including S100A2, S100A11, and S100A9." (PMID 35760899, 2022). "S100A9 usually works with S100A8 as a protein complex released due to apoptotic or cytotoxic effects, such as those of chemotherapeutic agents against various tumor cells." (PMID 33996571, 2021). "However, DLBCL clusters that correlated with tumor-conditioned monocytes highly expressed CD64, CD36, and S100A9 and thus presented similarities with IFNγ in-vitro polarized macrophages." (PMID 34975843, 2021). "CXCL1/2 also promoted the expression of paracrine factor S100A9, activated ERK1/2 and p70S60k, and promoted tumor growth, while blocking CXCL1/2 down-regulated the expression of these pro-survival factors and slowed tumor growth." (PMID 34630121, 2021). "Moreover, tumor-derived CCL2, CCL12, CXCL5, S100A8, and S100A9 promote the recruitment of immature myeloid cells to the tumor stroma, facilitating the enrichment of both MDSC subpopulations within the TME." (PMID 33430105, 2021). "We found that the infiltration of S100A9+ cells in both tumor and nontumor tissues could predict poor overall survival (P = 0.0329, tumor; P = 0.0003, nontumor) and a high recurrence risk (P = 0.0387, tumor; P = 0.0015, nontumor) in our tissue microarray analysis." (PMID 34157683, 2021). "Our data showed that most S100A9-expressing cells were neutrophils and macrophages (Mφs) in tumor tissues, and neutrophils in nontumoral tissues." (PMID 34157683, 2021). "Immunohistochemical staining showed that normal nasal mucosa tissues did not express S100A9, while S100A9 was highly expressed by tumor stromal cells in NKTCL." (PMID 34045609, 2021). "According to the TCGA-LIHC dataset analysis, S100A9 gene expression was significantly downregulated in tumor tissues compared to adjacent nontumor tissues." (PMID 34157683, 2021).
tumor (continued). "In support of visual inspection of the images, striking differences could be seen between the healthy stroma and tumor regions at 10829 Da and 13146 Da, which correspond to S100A8 and S100A9, respectively." (PMID 32733643, 2020). "Among low molecular weight proteins visualized, S100A8 and S100A9 were found to be expressed in the regions of tumor tissue but not in the surrounding healthy stroma of a post-operative microdissected tissue." (PMID 32733643, 2020). "Furthermore, both tumor cells and immune cells are able to secrete the S100A9 protein, stimulating the recruitment of myeloid-derived suppressor cells (MDSC) and the formation of a pre-metastatic niche in the tumor stroma." (PMID 33203795, 2020). "Given some expression of S100A8 and S100A9 in the tumor stroma and the distant healthy epithelium, these regions proved not to be clearly distinguishable from the tumor." (PMID 32733643, 2020). "High expression of S100A8 and S100A9 was found in the stroma cells, mainly monocytes, of pancreatic cancer, and the number of S100A8 positive stroma cells correlated with the Smad4 status of the tumour." (PMID 32722137, 2020). "The absence of an adaptive immune system did not decrease ear and skin acanthosis, the abundance of S100A9+ myeloid cells or the levels of proinflammatory mRNA transcripts induced by CARD14E138A." (PMID 32597759, 2020). "Following this unbiased and hypothesis-driven combined approach, we identified S100A8, S100A9, and LGALS3BP as proteins overexpressed in the tumor-initiating cell populations." (PMID 32503348, 2020). "We found that S100A9 expression was correlated to Dukes staging and metastasis status but not to tumor location and histological differentiation." (PMID 31620141, 2019). "We measured the expression of six different Zn-binding proteins in tissue microarrays (TMAs) from OPSCC patients by IHC in matched tumor and normal tissue, including: Lipocalin-1 (n = 63), AZGP1 (n = 68), albumin (n = 26), S100A7 (n = 53), S100A7 (n = 53), S100A8 (n = 51) and S100A9 (n = 50)." (PMID 31740720, 2019). "The study also assessed whether S100A9 and TNC levels have the potential to improve the efficiency of diagnosis when combined with other tumor biomarkers in CRC patients." (PMID 31632476, 2019). "Thus, we found that tumor S100A8 and S100A9 transcript levels as independent poor prognosticators in GBM." (PMID 30808902, 2019). "Other BAL neutrophil genes, such as IL17, S100a9, S100a8 and Arginase 1 were not statistic altered by the tumor growth." (PMID 31712726, 2019). "In addition, we also compared the serum S100A9 and TNC concentrations and some tumor characteristics, including the site of the lesions, tumor metastasis and tumor emboli." (PMID 31632476, 2019). "Consistent with RNA-seq data, the expression of SLN, TAC1, MYH8, and PGAM2 were down-regulated, whereas SDRC7, KRT16, S100A9, IL36G, and FABP9 were up-regulated in both blood (Animal #9, #11, and #12) and skin (Animal #6, #7, and #8)-induced tumours relative to normal skin controls." (PMID 31340720, 2019). "S100A9 mRNA levels were significantly higher in tumor specimens from patients with OS than in non-neoplastic tissues." (PMID 31055998, 2019). "In addition, CCL2, secreted by primary tumor cells, stimulates lung ECs to release S100A8 and S100A9, leading to paracrine upregulation of SAA3, and consequently the formation of the premetastatic niche." (PMID 30654796, 2019). "The mRNA levels of RBL2 (P=0.2687), SASH1 (P=0.0859), S100A8 (P=0.2198) and S100A9 (P=0.0731) were not significantly different between ER+-cancer tissues and ER+-tumor-adjacent tissues." (PMID 29416786, 2018).
tumor (continued). "In addition, mice sacrificed at the end of the 13th or 18th week showed that blockade of S100a9 significantly inhibited AOM/DSS-induced colon shortening, and decreased the tumor rate and tumor numbers of the CAC mouse model." (PMID 29326691, 2017). "Indeed, estrogen induces neutrophil expression of a plethora of genes encoding protumoral cytokines/chemokines(e.g. CXCL1, CXCL2, S100A8, S100A9), matrix metalloproteinases(MMP3, MMP9) and COX-2 that are all known to promote tumor growth and metastasis." (PMID 28429725, 2017). "Mice lacking S100A9 have apparently reduced infiltration of CD11b(+)Gr1(+) cells within tumors and pre-metastatic organs showed lower tumor incidence, growth and migration." (PMID 27020242, 2016). "While we demonstrate the effects mediated intracellularly through alterations in calcium levels, tumor-derived S100A8 and S100A9 are likely to have other effects both intracellular and/or extracellular in the tumor microenvironment, both in our model and in other tumor settings." (PMID 27086923, 2016). "Monocytes/macrophages from tumor-bearing livers, but not normal livers, expressed high levels of TNFα and stimulated S100a8 and S100a9 expression." (PMID 27086923, 2016). "Interestingly, 4 of the top 5 up-regulated proteins in tumor TIF were all S100 family members, including S100P (ratio = 40.9), S100A9 (ratio = 19.0), S100A8 (ratio = 5.3) and S100A12 (ratio = 4.5)." (PMID 27216119, 2016). "Although S100A9 is pro-tumorigenic regardless of its presence in tumor or stroma, the promoting effects were mainly on cancer cell migration and invasion." (PMID 26315114, 2015). "Consistent with no stimulation of high tumorigenic HSC-3 proliferation in vitro, S100A9 had no tumor promoting effect on these tumors." (PMID 26315114, 2015). "At the same time, Western blot assay has confirmed that S100A9/Calgranulin B shown an increased expression in tumor tissues as opposed to peritumoral tissues." (PMID 25298751, 2014). "The levels of calcium binding proteins S100A8 and S100A9 increase in cancer, including PDAC; although mainly expressed by tumor-infiltrating inflammatory cells, they may also be expressed by PDAC cells." (PMID 24670043, 2014). "Some authors reported that Stat3-dependent S100A9 up-regulation enhances MDSC generation in vitro and that the immune system of mice lacking S100A9 have a greater ability to reject the tumor implant." (PMID 25538892, 2014). "We performed immunohistochemical (IHC) staining to detect the expression of S100A8 and S100A9 in sections of 42 pairs of samples (CRC and matching distal normal tissues) and found that S100A8 and S100A9 were elevated in tumor cells of CRC tissues compared with the matching distal normal tissues." (PMID 23637971, 2013). "In addition, paclitaxel-induced inhibition of p38 MAPK activity decreases the production of S100A9 and TNF-α by MDSCs, resulting in reduced tumor burden and increased animal survival." (PMID 24339824, 2013). "Take together, our results provide important information regarding the roles of S100A8 and S100A9 in malignancy and should be paid much attention considering that S100A8 and S100A9 has been increasingly recognized as tumor markers and also as new molecular targets for developing cancer therapeutics." (PMID 23637971, 2013). "However, the molecular mechanism, how glyphosate contributes in tumor promotion, and regulation of S100A6, S100A9, and SOD 1 remain elusive and require more detailed analysis of the mechanism." (PMID 24073338, 2013). "Interestingly, tumor-induced up-regulation of S100A8 and S100A9 proteins were found in myeloid precursor cells and have contributed to the recruitment and accumulation of myeloid-derived immune-suppressor cells at sites of tumor formation." (PMID 23613688, 2013). "There was no obvious relation between the number of S100A9 stained immune cells and tumor Gleason score." (PMID 22470535, 2012).
tumor (continued). "Moreover, potential secretion of TNFα, VEGF-A and TGF-β1 from primary tumours induced S100A8 and S100A9, which in turn stimulated the enrichment of other inflammatory chemo-attractants." (PMID 23157946, 2012). "In the EL-4 lymphoma model tumor growth inhibition was observed in S100A9−/− and TLR4−/−, but not in RAGE−/− animals lacking an alternative S100A9 receptor." (PMID 22470535, 2012). "Therefore, we suggest that it is primarily the interaction between S100A9 and TLR4 that promotes tumor growth in our studies." (PMID 22470535, 2012). "When this analysis was extended to TGFβ expression at the protein level we found that while TGFβ serum levels in C57BL/6 and RAGE−/− mice increased in tumor-inoculated animals it did not in S100A9−/− and TLR4−/− animals." (PMID 22470535, 2012). "Thus, we decided to continue our studies on the effect of S100A9 and TLR4 on tumor growth in the EL4 tumor system." (PMID 22470535, 2012). "Similar expression profiles were also seen across all tumour types for S100A8 and S100A9 but this could be attributed to their function in which they form a heterodimer complex." (PMID 18781180, 2008). "Notably, TGFB1, TGFB2, TGFB3, S100A8, S100A9, IL6, and PTGES secreted by PMN-MDSCs exhibit both protumorigenic and immunosuppressive properties, playing significant roles in promoting tumor growth and evading immune responses." (PMID 41280721, 2025). "Similarly, S100A9 + MDSCs activate the ERK/NF-κB pathway in HCC cells, creating a self-sustaining “ETV5-S100A9-ERK/NF-κB” loop via ETV5 upregulation, which accelerates tumor progression." (PMID 41019983, 2025). "Overall, our results, for the first time, show that S100A9 enhances SCLC progression and metastasis by altering the tumor microenvironment, and its inhibition using tasquinimod alone or in combination with chemotherapy could be developed as a promising therapeutic strategy for SCLC." (PMID 41173834, 2025). "Notably, under neoplastic conditions, S100A8 and S100A9 are not solely derived from mesenchymal cells but are also highly expressed in tumor epithelial cells." (PMID 38817853, 2024). "This study integrated HCC scRNA-seq and RNA-seq data and developed a tumor classification signature (MPCD index) based on extensive bioinformatics analysis and machine learning algorithms, and found four prognostic genes for HCC, S100A9, FYN, LGALS3, and HMOX1." (PMID 39795978, 2024). "Although the apoptosis increased in EACC, S100A8 and S100A9 might still play a more prominent role in cell proliferation and pro-tumor function, which can explain its negative correlation with apoptosis." (PMID 39575241, 2024). "Notably, S100A8 and S100A9 were not confined to increased expression solely in mesenchymal immune cells; their expression was also notably elevated within tumor cells, exceeding levels found in normal tissues." (PMID 38817853, 2024). "To demonstrate the therapeutic potential of S100A9 inhibitor tasquinimod in combination with venetoclax as a novel therapeutic approach for unfit/frail AML patients, we tested the combination on KG-1a and MOLM-13 cell lines, and 5 primary patient samples with variable tumor loads." (PMID 38110349, 2023). "Thus, we speculated that S100a9 may rescue exhausted CD8+ T cells via PD-1/PD-L1 blockade and possibly also elicit powerful anti-tumor responses." (PMID 36810783, 2023). "Multivariate analyses of the prognostic value of the S100A9/THBS4 predictor for the 3-year metastasis-free survival by a Cox regression model that includes potential confounding factors (including patient age and gender, tumor stage and history of tobacco smoking)." (PMID 38022675, 2023). "We detected 24 genes across the tumor tROIs that showed a high CV (i.e., were among the genes with the top 20% highest CV in seven out of seven cases), such as multiple collagens (COL1A1, COL1A2, COL3A1, COL5A1, COL5A2), S100A8, S100A9, FN1, or Early growth response protein 1 (EGR1)." (PMID 37511126, 2023).